NKAIN1 (sodium/potassium transporting ATPase interacting 1)
Synonyms: FAM77C; FLJ12650
Tractability: Antibody: UniProt places it where antibodies can reach, with high confidence; UniProt predicts a signal peptide or a membrane-spanning region; its Gene Ontology location is reachable by antibodies, with medium confidence.
Gene: Protein-coding gene on chromosome 1 (31,179,344 to 31,239,966, reverse strand). Ensembl gene ENSG00000084628.
Subcellular location: Cell membrane
Gene Ontology:
Molecular function: ATPase binding
Biological process: regulation of sodium ion transport
Cellular component: plasma membrane
Genetic constraint (gnomAD): Loss-of-function variants: 13 observed, 25.94 expected, observed/expected ratio (o/e) 0.5, 90% interval 0.32 to 0.8. The upper end of that interval is the gene's LOEUF score, 0.8, which puts it in group 3 of 6, group 1 being the genes least tolerant of losing a copy. Missense variants: 193 observed, 236.75 expected, observed/expected ratio (o/e) 0.82, 90% interval 0.72 to 0.92. Synonymous variants: 104 observed, 97.24 expected, observed/expected ratio (o/e) 1.07, 90% interval 0.91 to 1.26.
Homologues: Orthologues: chimpanzee NKAIN1 (100% identical), guinea pig NKAIN1 (99% identical), mouse Nkain1 (99% identical), pig NKAIN1 (99% identical), macaque NKAIN1 (93% identical), dog NKAIN1 (89% identical), tropical clawed frog nkain1 (82% identical), zebrafish nkain1 (77% identical), rat Nkain1 (67% identical), Drosophila melanogaster NKAIN (46% identical), Caenorhabditis elegans gldi-7 (30% identical). Paralogues in human: NKAIN2 (71% identical), NKAIN3 (57% identical), NKAIN4 (57% identical).
Diseases named in the same sentence as NKAIN1 in open-access papers:
NKAIN1 is named in the same sentence as 10 diseases in open-access papers, as found by Europe PMC text mining. Sharing a sentence is not in itself a finding about the gene and the disease. The quoted sentences say what the papers report.
prostate carcinoma (3 papers, 2017 to 2025). A carcinoma that arises from epithelial cells of the prostate gland. "Previous research has demonstrated the utility of NKAIN1 mRNA expression in urine sediment for early clinical diagnosis and in cancer tissue for immunotherapy in prostate cancer patients." (PMID 41350575, 2025). "NKAIN1 (Na+/K+ transporting ATPase interacting 1) has been proposed as a prostate cancer marker, but also has some restricted neuronal expression." (PMID 28871274, 2017).
breast carcinoma (2 papers, 2010 to 2025). "NRIP3, TMC5, REEP1 and NKAIN1, whose expression had not previously been described in breast cancer, were also deregulated in the PIK3CA-mutated breast tumors." (PMID 21209903, 2010).
breast tumors (1 paper, 2010). "Thirty-eight of these 39 unique genes were over-expressed in ERα-positive breast tumors with PIK3CA mutations, 16 being up-regulated at least 3-fold, while only one gene (NKAIN1, encoding Na+/K+ ATPase interacting protein) was down-regulated, with a FC of 3.52." (PMID 21209903, 2010). "Indeed, the 19-gene set including NKAIN1 classified the 249 breast tumors significantly more accurately than the set of 18 up-regulated genes without NKAIN1 (accuracy 59% and 57%, Χ2 test P values of 0.0006 and 0.0141, respectively)." (PMID 21209903, 2010).
gastric cancer (1 paper, 2025). A primary or metastatic malignant neoplasm involving the stomach. "To further assess the association of NKAIN1 protein expression with patient’s characteristics, we stratified the 305 gastric cancer patients into high (n = 101) and low (n = 204) NKAIN1 protein expression subgroups." (PMID 41350575, 2025). "Given the variability in NKAIN1 protein expression in gastric cancer, its association with patients’ clinical characteristics and prognosis were explored." (PMID 41350575, 2025). "To explore the association between NKAIN1 protein expression and the abundance of TIICs and immune checkpoints, we conducted mIHC staining using gastric cancer TMAs." (PMID 41350575, 2025). "To date, limited research has been conducted on the NKAIN1 protein and its association with tumors, particularly in the context of clinical gastric cancer." (PMID 41350575, 2025). "To elucidate the association between NKAIN1 protein expression in gastric cancer and clinical features, we conducted multiplex immunohistochemistry (mIHC) with gastric cancer tissue microarray (TMA)." (PMID 41350575, 2025). "Gene expression analysis, multiplex immunohistochemistry using tissue microarrays, and Quantitative Pathology Imaging System were conducted for determining the expression of NKAIN1 in gastric carcinoma tissues and association with patient outcomes." (PMID 41350575, 2025). "Overall, the study findings identify NKAIN1 as a prognostic indicator and a promising candidate for immunotherapy in gastric cancer." (PMID 41350575, 2025). "Given that different tissue cells express varying levels of mRNA and produce proteins with distinct biological activities, our study aimed to investigate NKAIN1 protein expression in the TME of gastric cancer." (PMID 41350575, 2025). "Using X-tile software based on the 5-year OS of stomach cancer patients, we determined a cutoff of 45 for NKAIN1 protein expression in cancer cells: scores of 0–45 were categorized as low expression, and 46–100 as high expression." (PMID 41350575, 2025). "We conducted mIHC staining analysis on sections of human gastric cancer TMAs to assess NKAIN1 protein expression and visualize tumor-infiltrating immune cells (TIICs) and immune checkpoints (PD-1, PD-L1 and CTLA-4)." (PMID 41350575, 2025). "Our analysis of TCGA online data revealed a correlation between high expression of the Na+/K + transporting ATPase interacting 1 gene (NKAIN1) in gastric cancer tissues and patients’ poor prognosis." (PMID 41350575, 2025). "This study aims to investigate the relationship between NKAIN1 levels in the tumor microenvironment and gastric carcinoma patients characteristics." (PMID 41350575, 2025). "In this study, we used bioinformatics and identified NKAIN1 mRNA as a promising prognostic biomarker in human gastric carcinoma." (PMID 41350575, 2025). "In conclusion, this study supports NKAIN1 as a prognostic marker and promising target for immune therapy in stomach carcinoma." (PMID 41350575, 2025). "Importantly, the increased NKAIN1 protein expression was identified as an independent prognostic factor for adverse clinical outcomes in gastric cancer." (PMID 41350575, 2025). "Additionally, we used the Spearman correlation method to assess the relationship between NKAIN1 protein expression in the tumor immune microenvironment and immune checkpoint markers of gastric carcinoma." (PMID 41350575, 2025). "Therefore, we propose that NKAIN1 may serve as a potential candidate biomarker for oncogenesis in gastric cancer." (PMID 41350575, 2025). "Furthermore, K-M analysis with log-rank tests demonstrated that high NKAIN1 protein expression and advanced TNM stage were correlated with poorer outcomes in gastric cancer patients." (PMID 41350575, 2025). "The study findings indicated a significant increase in NKAIN1 expression in gastric carcinoma tissues compared to non-tumor stomach tissues." (PMID 41350575, 2025).
cancer (4 papers, 2010 to 2025). A tumor composed of atypical neoplastic, often pleomorphic cells that invade other tissues. "However, significant associations were found between NKAIN1 protein expression in cancer nests and CTLA-4 (r = 0.246, P < 0.001) as well as PD-L1 expression (r = 0.215, P < 0.001) within cancer nests, demonstrating statistical significance." (PMID 41350575, 2025). "Our data revealed an association between NKAIN1 protein levels, cancer invasion, and tumor stage." (PMID 41350575, 2025). "Subsequently, we investigated the correlation between NKAIN1 protein expression in cancer cells and the immune microenvironment in gastric cancerous tissue through statistical analysis." (PMID 41350575, 2025). "Analysis of stained slides confirmed that NKAIN1 protein expression was predominantly observed in the plasma and membrane of cancer cells, showing varying degrees of positivity." (PMID 41350575, 2025). "NKAIN1 protein was positive staining on tumor stromal cells without statistical difference in a small number of cancer tissues." (PMID 41350575, 2025).
tumor (1 paper, 2025). "Our findings revealed that high NKAIN1 protein expression was not only significantly correlated with deeper tumor invasion and advanced TNM stage but was linked to poorer short-term prognosis." (PMID 41350575, 2025). "Univariate assessment revealed associations between OS rates and NKAIN1 protein presence (HR: 1.848, P < 0.001), tumor differentiation (HR: 1.838, P = 0.004), T (HR: 2.005, P < 0.001)/N (HR: 2.021, P < 0.001)/M (HR: 4.035, P = 0.001), and TNM stage (HR: 2.693, P < 0.001)." (PMID 41350575, 2025). "We found that high NKAIN1 expression was associated with moderate HER2 expression (χ2 = 9.636, P = 0.008), deeper tumor invasion (χ2 = 9.438, P = 0.024), moderate to extensive lymph node metastases (χ2 = 8.632, P = 0.035), and advanced TNM stage (χ2 = 8.753, P = 0.013)." (PMID 41350575, 2025).
NKAIN1 also shares sentences with these, for which no sentence is quoted: neurodevelopmental disorder (1 paper); ovarian carcinoma (1); pancreatic cancer (1); stomach cancer (1).